MMP9 (matrix metallopeptidase 9)
Diseases named in the same sentence as MMP9 in open-access papers (continued):
Sharing a sentence is not in itself a finding about the gene and the disease.
Anxiety (22 papers, 2009 to 2026). Intense feelings of nervousness, tension, or panic often arise in response to interpersonal stresses. "Decreased MMP9 levels result in decreased neuronal differentiation in the hippocampus and may cause increased anxiety in mice." (PMID 38993198, 2024). "This study is to examine whether using MMP9 as an adjunct to FOBt can improve the accuracy of screening and reduce the number of false positive tests that cause anxiety and require invasive and potentially harmful investigation." (PMID 19175925, 2009). "This study is to examine whether using MMP9 as an adjunct to FOBt improves the accuracy of screening and reduces the number of false positive tests that cause anxiety and require invasive and potentially harmful investigation." (PMID 19175925, 2009). "Our z-score analysis of the anxiety and the depressive-like phenotype shows a marked sex-dependent effect in depressive-like behavior associated to the deletion of MMP-9, while the overexpression of MMP-9 showed a sex-dependent effect on anxiety." (PMID 40405318, 2025). "MMP-9 OE female group presented a lower score in anxiety-like behavior than WT female (p < 0.001) and MMP-9 OE male mice (p < 0.001)." (PMID 40405318, 2025). "With respect to MMP-9-overexpressing mice, females presented decreased innate anxiety (elevated plus maze)." (PMID 40405318, 2025). "MMP-9 knockout female mice displayed increased innate anxiety (open field test), decreased behavioral despair (tail suspension test)." (PMID 40405318, 2025). "Our study highlights the impact of MMP-9 expression levels on anxiety and depressive-like behaviors." (PMID 40405318, 2025). "In our study, we did not observe any statistically significant differences in innate anxiety in male MMP-9 KO mice, which is consistent with previous studies that reported no alterations in anxiety in MMP-9 KO mice." (PMID 40405318, 2025). "For example, female C57BL/6J mice, which exhibit higher basal MMP-9 brain levels, show lower anxiety in the elevated plus-maze test than other strains with lower MMP-9 brain levels and greater anxiety." (PMID 40405318, 2025). "Male MMP-9-overexpressing mice presented greater conflict-based anxiety (novelty-suppressed feeding test) than control mice did." (PMID 40405318, 2025). "Our results concur with the observation that the genetic or pharmacological inactivation of MMP9 decreases basal anxiety, despair and sociability in stressed animals but also dampens the behavioral response of venlafaxine." (PMID 37365183, 2023). "Remarkably, increased PV levels and enhanced PNN formation in the auditory cortex of Fmr1 KO mice following MMP-9 inhibition is correlated with decreased anxiety and hyperactivity during adolescence (PND 27–28)." (PMID 37188005, 2023). "It has been shown in mouse models for FXS that levels of MMP9 were increased and this increase was negatively correlated with behavioral improvement in young mice in general cognition and anxiety." (PMID 36143345, 2022). "As such, MMP9 appears to mediate certain neurobehavioral deficits in AD, such as anxiety and social recognition memory, but these effects are independent of Aβ levels in the brain." (PMID 34034683, 2021). "In the current studies, MMP9 modulation in AD animals improved sociability and social recognition memory, particularly in male mice, in addition to reducing anxiety, while spatial learning and memory was unaffected." (PMID 34034683, 2021). "Treatment with the MMP9 inhibitor SB-3CT in E4FAD mice led to reduced anxiety compared to placebo using the elevated plus maze." (PMID 34034683, 2021). "In particular, TIMP-1 was shown to impact memory and cognition in mice in an olfactory maze test and MMP-9 knockout mice exhibited lower anxiety in EPM and higher vertical activity in an open field test." (PMID 33384653, 2020). "In addition, a phenotype resilient to anxiety is observed in female MMP-9 OE mice, that aligns with previous findings." (PMID 40405318, 2025).
Anxiety (continued). "Taken together, these results suggest that MMP-9 plays a sex-dependent role in anxiety." (PMID 40405318, 2025). "In this sense, although the reduction of BDNF, mTOR pathway activation has been associated to an increased anxiety-like behavior, other hippocampal neural markers might be correlated with the lower anxiety elicited by female MMP-9 OE mice." (PMID 40405318, 2025). "Interestingly, female MMP-9 KO mice presented increased innate anxiety, but only in the open field test." (PMID 40405318, 2025). "The lower level of innate anxiety observed in our female MMP-9 OE mice aligns with these findings." (PMID 40405318, 2025). "Interestingly, anxiety is among neuropsychiatric FXS associated symptoms and inhibition of MMP-9 activity by minocycline showed an improvement of anxiety in individuals with FXS18,54." (PMID 36100610, 2022). "However, gel zymography seems to be a more sensitive method to detect differences in MMP-9 active form between FXS and healthy controls as well as the association with aberrant behavior, and anxiety related symptoms." (PMID 36100610, 2022). "In total, while MMP9 inhibition did improve specific neurobehavioral deficits associated with AD, such as anxiety and social recognition memory, modulation of MMP9 did not alter spatial learning and memory or Aβ tissue levels in AD animals." (PMID 34034683, 2021). "In the present studies, 5xFAD/MMP9KO mice had significantly lower locomotor activity compared to the 5xFAD mice as measured by distance travelled and average velocity, again suggesting MMP9 may be influencing anxiety-related behavior." (PMID 34034683, 2021). "Owing to this limitation, it is not certain whether the observed effect on anxiety in the current studies was caused by the inhibition of MMP9 activity or another effect of the drug." (PMID 34034683, 2021). "In contrast to the more anxious phenotype observed in the open field test in female MMP-9 KO mice, female MMP-9 OE mice displayed lower innate anxiety which was more evident in the elevated plus maze test." (PMID 40405318, 2025). "In our study, 17 core common targets of ACG and anxiety were predicted, of which ESR1, SRC, AKT1, MAPK8, EGFR, and MMP9 belong to the prolactin and estrogen signaling pathways." (PMID 35624976, 2022). "Deletion of the MMP9 gene in 5xFAD mice also reduced anxiety using the open field test, in addition to improving sociability and social recognition memory, particularly in male mice, as assessed through the three-chamber task, indicating certain behavioral alterations in AD may be mediated by MMP9." (PMID 34034683, 2021). "We observed in female mice an opposite effect to the expected phenotype regarding anxiety, with higher anxiety in mice lacking MMP-9 and lower anxiety in mice that overexpress this protein." (PMID 40405318, 2025). "Additionally, there was a reverse relation between anxiety and PANS and the level of MMP-9 (r: -0.344, P=0.02; r: -0.309, P= 0.026, respectively) in patients with NPSLE." (PMID 38463908, 2024). "The altered anxiety in the E4FAD mice indicates that treatment with SB-3CT may be efficacious, however, due to limitations in detection, the proteolytic activity of MMP9 in the brain could not be measured and we could not confirm target engagement." (PMID 34034683, 2021).
Aortic dissection (22 papers, 2013 to 2025). Aortic dissection refers to a tear in the intimal layer of the aorta causing a separation between the intima and the medial layers of the aorta. "A combined detection model using preoperative blood CRP, D-dimer, and serum MMP-9 concentrations showed AUC value of 0.88 with 70.70% sensitivity and 96.84% specificity for mortality of patients with Type A aortic dissection within 1 year." (PMID 39910669, 2025). "The expression of MMPs, particularly MMP2 and MMP9, combined with inflammatory cell infiltration, are also characteristics of aortic dissection pathogenesis." (PMID 40680508, 2025). "Following surgery for acute aortic dissection, platelets release MMP-9 to reprogram monocytes, thereby contributing to postoperative recovery." (PMID 39712025, 2024). "The findings of the present study suggest a strong association between AT1-AAs and MMP-9 levels in patients with acute aortic dissection, because the levels of MMP-9 in AT1-AA–positive patients increased significantly." (PMID 34596673, 2021). "Ang II, NA, MMP-2, MMP-9 of the aorta sample obtained during operation from aortic dissection patients were detected by High Performance Liquid Chromatography and ELISA and compared with controls." (PMID 24194850, 2013). "Several investigators, applying both immunohistochemical techniques and zymography on acute dissection specimens, have reported increased MMP-9 and −2 expression at the site of the initial tear in patients with aortic dissection." (PMID 23642232, 2013). "They found a number of matrix metalloproteases (MMP-19, MMP-12, MMP-9) were differentially expressed in acute aortic dissection patients." (PMID 23642232, 2013). "Preliminary studies have detected increased plasma levels of MMP8 and MMP9 in patients with acute aortic dissection (AAD)." (PMID 23442769, 2013). "This is consistent with findings that neutrophil-derived MMP-9 can trigger acute aortic dissection." (PMID 41584293, 2025). "The Nlrp3-caspase 1 complex is activated in the condition of aortic dissection and participates in the process of aortic damage by degrading smooth muscle cell contractile protein, promoting macrophage inflammation and MMP9 expression and intensifying extracellular matrix degradation." (PMID 35211530, 2022). "Plasma levels of MMP8 and MMP9 in acute aortic dissection versus alternative diagnoses." (PMID 23442769, 2013). "LINC01605 is upregulated in a mouse model of aortic dissection and participates in the cellular processes of migration, proliferation and autophagy associated with aortic dissection by modulating the expression of genes such as SGK1, MMP‐2, MMP‐9, α‐SMA, SM22α, LC3B and p62." (PMID 41294029, 2025). "Serum MMP9 represents the leakage of enzyme into the bloodstream during periods of matrix catabolism and its elevation may reflect a more active state of degeneration of the aortic wall in the natural history of aortic dissection." (PMID 30497388, 2018). "Following the acute phase of aortic dissection, there is an increase in circulating MMP-9 levels, with plasma MMP-9 expression reaching its maximum approximately 2 weeks after the onset of symptoms." (PMID 38700707, 2024). "It has been reported that when aortic dissection occurs, the serum levels of MMP1, MMP2, MMP3, MMP8, and MMP13 are increased, and the expression of MMP9 in the cytoplasm of smooth muscle cells in the aortic wall is enhanced." (PMID 35463768, 2022). "Nine proteins (Lumican, FGL1, PI16, MMP9, FBN1, MMP2, VWF, MMRN1, and PF4) related to the pathogenesis of aortic dissection were identified by David /Ease and String techniques as candidate biomarkers for verification test." (PMID 35910577, 2022). "Kurihara and colleagues recently reported that MMP-9 was significantly elevated in blood samples from acute aortic dissection patients than in those from the patients with nonruptured chronic aortic aneurysm or healthy volunteers." (PMID 23642232, 2013).
Aortic dissection (continued). "In addition, CRP levels positively correlate with DD levels in aortic dissection, suggesting the presence of a strict relationship between these two factors in the pathophysiology of the complication and with plasma MMP8 and MMP9 in patients suspected of dissection." (PMID 35892496, 2022). "However, there is lacking research on serum TLR4 levels in acute aortic dissection (AAD) patients, and the performance of serum MMP9 and TLR4 for the diagnosis of AAD is still unknown." (PMID 30497388, 2018).
chondrosarcoma (22 papers, 2008 to 2026). A malignant cartilaginous matrix-producing mesenchymal neoplasm arising from the bone and soft tissue. "This study demonstrates that MMP-9 expression in chondrosarcoma is associated with a lower occurrence of metastases, lower grading and a better survival of patients with chondrosarcoma." (PMID 29316907, 2018). "Our findings suggest that the expression of MMP-9 is associated with clinical outcome parameters in chondrosarcoma." (PMID 29316907, 2018). "Positive expression of MMP-9 was associated with increased metastatic free survival time of patients with chondrosarcoma (p = 0.047) in Kaplan-Maier analysis." (PMID 29316907, 2018). "Our findings demonstrate CCN6-induced enhancement of MMP-9 expression and secretion in human chondrosarcoma cells; the loss of MMP-9 expression significantly suppressed CCN6-induced cell migration and invasion activity." (PMID 30237403, 2018). "High levels of MMP-9 expression were associated with a better histological differentiation of chondrosarcoma—more differentiated tumor type (grades I and II) showed higher MMP-9 expression than grade III chondrosarcoma." (PMID 38138968, 2023). "One study found that MCP-1 can induce cancer cell migration through the upregulation of MMP-9 in chondrosarcoma." (PMID 33228783, 2020). "Opn has been shown to increase the expression of MMP9 via β3 integrins in Neuro2A cells, human chondrosarcoma cells, cardiac, skeletal muscles, and endometrial cells." (PMID 32512754, 2020). "There was significant correlation between the expression of MMP-9 and histological grading of chondrosarcoma (p = 0.011)." (PMID 29316907, 2018). "Our data show that NF-κB activation plays an important part in CCN6-induced migration and MMP-9 expression in human chondrosarcoma cells and that blocking the NF-κB-dependent signaling pathway inhibits CCN6-induced MMP-9 expression and cancer metastasis." (PMID 30237403, 2018). "It appears that CCN6 acts via the PI3K/Akt-dependent signaling pathway to enhance MMP-9 mRNA expression, cell migration, and invasion of human chondrosarcoma cells." (PMID 30237403, 2018). "Our findings reveal an important mechanism underlying CCN6-induced metastasis and they highlight the clinical significance between CCN6 and MMP-9 in regard to human chondrosarcoma." (PMID 30237403, 2018). "Our results indicate that endogenous CCN6 activates the PI3K/Akt/mTOR/NF-κB signaling pathway and augments MMP-9-dependent lung metastasis of chondrosarcoma in vivo." (PMID 30237403, 2018). "Better differentiated chondrosarcoma (grade I and grade II) expressed more MMP-9 then high-grad chondrosarcoma with poorer differentiation (grade III)." (PMID 29316907, 2018). "In this current study, we explored the role of CCN6 in metastasis and upregulation of MMP-9 in human chondrosarcoma cells." (PMID 30237403, 2018). "This indicates that the PI3K/Akt/mTOR signaling pathway is required for CCN6-induced MMP-9 expression and chondrosarcoma cell metastasis." (PMID 30237403, 2018). "We show how CCN6 promotes chondrosarcoma cell migration and invasion via matrix metallopeptidase-9 (MMP)-9 expression." (PMID 30237403, 2018). "This suggests that CCN6 increases MMP-9 expression and induces cell metastasis in human chondrosarcoma cells via the PI3K/Akt/mTOR/NF-κB signaling pathway." (PMID 30237403, 2018). "The positive correlation of metastatic potential and the expression of MMP-9 was reflected in the survival analysis in patients with chondrosarcoma." (PMID 29316907, 2018). "Both PD98059 and U0126 inhibited osteopontin-induced MMP-9 upregulation and migration of human chondrosarcoma cells." (PMID 22577336, 2012). "Osteopontin is a bone matrix protein that increases the migration and expression of matrix metalloproteinase (MMP)-9 in grade II human chondrosarcoma cells through pERK1/2 pathway." (PMID 22577336, 2012).
chondrosarcoma (continued). "In a study regarding whether OPN regulated MMP expression, OPN was observed to promote the migration of human chondrosarcoma cells by upregulating MMP-9 via nuclear factor-κB-dependent pathways." (PMID 39533922, 2024). "In addition, we observed a strong correlation between CCN6 and MMP-9 expression in human chondrosarcoma tissue and preclinical analyses." (PMID 30237403, 2018). "Indeed, we observed that p85, Akt, and mTOR siRNAs reduced MMP-9 expression, and inhibited chondrosarcoma cells migration and invasion." (PMID 30237403, 2018). "Moreover, MMP-1, MMP-7 and MMP-9 expression was found to be highest in the invasive protrusions of chondrosarcomas." (PMID 29361725, 2018). "We examined whether NF-κB activation plays a role in CCN6-induced activation of the signaling transduction pathway and subsequent chondrosarcoma cell migration, invasion, and enhanced MMP-9 expression." (PMID 30237403, 2018). "In conclusion, MMP-1, MMP-3 and MMP-9 are often expressed in chondrosarcoma." (PMID 29316907, 2018). "Thus, the PI3K/Akt/mTOR signaling pathway must be activated for CCN6-induced enhancement of cell migration, invasion, and MMP-9 production in human chondrosarcoma cells." (PMID 30237403, 2018). "Similar to OS and ES, the expression of MMPs such as MMP-1, MMP-2, MMP-3, MMP-7, MMP-9, and MMP-14 is also found in biopsy specimens from patients with chondrosarcoma." (PMID 38138968, 2023). "A previous study revealed that in chondrosarcoma, the MCP-1/CCR2 axis requires c-Raf, MEK, ERK signal pathways for MMP-9 overexpression." (PMID 33228783, 2020). "In this current study, stimulation of chondrosarcoma cell lines with CCN6 promoted cell motility and MMP-9 expression, which in turn activated the PI3K/Akt/mTOR/NF-κB signaling pathway." (PMID 30237403, 2018). "In consideration of semi quantitative scoring 64% of chondrosarcoma were scored as positive for MMP-1, 46% for MMP-3, 61% for MMP-9." (PMID 29316907, 2018). "The purpose of this study was to investigate immunohistochemicaly the influence of MMP-1, MMP-3, MMP-9 and MMP-13 expression on prognostic parameter in chondrosarcoma." (PMID 29316907, 2018). "Pretreating chondrosarcoma cells with PI3K inhibitors (Ly294002, wortmannin) or siRNAs abolished CCN6-mediated cell migration, invasion, and MMP-9 mRNA expression, while transfection of cells with p85 or Akt siRNAs inhibited p85 and Akt expression." (PMID 30237403, 2018). "rOPN increased MMP-9 expression and migration of JJ012 chondrosarcoma cells through αvβ3 integrin, focal adhesion kinase (FAK), MAPK/ERK kinase (MEK), extracellular signal-regulated kinase (ERK) and NF-κB signaling." (PMID 29361725, 2018). "After 5 years, 19% of chondrosarcoma with high MMP-9 expression developed metastasis, compared to 62% with lower MMP-9-expression." (PMID 29316907, 2018). "Expression levels of MMP-1, MMP-2, MMP-3, MMP-7, MMP-8, MMP-9, and MMP-13 are high in human chondrosarcoma cells." (PMID 30237403, 2018). "Other studies on Huh7 cells and chondrosarcoma cells have also revealed a similar molecular mechanism in which CCL2 regulates MMP2 and MMP9 expression through the PI3K/Akt and NF-κB signaling pathways." (PMID 23941552, 2013). "A previous study showed that MMP-1, MMP-2, MMP-3, MMP-9, and MMP-13 were expressed in high quantities in human chondrosarcoma cells." (PMID 23892595, 2013). "In chondrosarcoma cells, tumor necrosis factor (TNF)-α had a stimulatory effect on MMP-9 and insignificant effect on MMP-2 and interleukin (IL)-1β stimulated MMP-9 and MMP-2." (PMID 24085323, 2013). "Studies have shown that MMP-1, MMP-2, MMP-3, MMP-9, and MMP-13 exhibit high degrees of expression in human chondrosarcoma cells." (PMID 23892595, 2013). "Furthermore, while the EMT markers including Slug, MMP9, MMP2, CD44, N-Cadherin, and vimentin were suppressed by BTZ concomitant increased expression of E-Cadherin was detected in chondrosarcoma cells." (PMID 33674562, 2021).